LRP1B (LDL receptor related protein 1B)
Diseases named in the same sentence as LRP1B in open-access papers (continued):
Sharing a sentence is not in itself a finding about the gene and the disease.
tumor (continued). "It is worth mentioning that RBM10, KEAP1 and LRP1B, regarded as tumor suppressor genes, were more frequently mutated in aged group compared with young group, which may contribute to the high incidence of LUAD in the elderly." (PMID 35371328, 2022). "Moreover, previous studies have suggested a close relationship between LRP1B mutations and tumor mutational burden (TMB), which can predict prognosis and therapy targets in cancer patients." (PMID 35389768, 2022). "Interestingly, LRP1B mutations, which has been reported to be associated with high tumor mutation burden and better response to immunotherapy, were only detected from 5 SPA patients (p=0.001)." (PMID 33976731, 2021). "We found that co-mutation of FAT3 and LRP1B has prominent significance, which can increase somatic mutational load, boost cytotoxicity and tumor immunogenicity, facilitate lymphocyte infiltration in the microenvironment, and significantly influence the outcome of immunotherapy." (PMID 35069585, 2021). "In the process of tumor development, LRP1B mutation may affect the content of N2 neutrophils in HCC patients through some unknown mechanism, which may be one reason for the poor prognosis of patients with LRP1B mutation." (PMID 34093808, 2021). "As many pathways are involved in tumor formation, poor survival associated with LRP1B mutation may be associated with many signaling pathways activated in HCC." (PMID 34093808, 2021). "In conclusion, these mechanism-related results could help identify appropriate corresponding drugs to prevent tumor progression as a result of the characteristics introduced by LRP1B mutation in STAD patients." (PMID 33827485, 2021). "The simultaneous prominence of the three types cells, CD8+ T cells, activated CD4+ memory T cells and M1 macrophages, implying that co-mutation of FAT3 and LRP1B can be used to predict the cytotoxic effect of lymphocytes against tumor cells and the beneficial response of immunotherapy in LUAD." (PMID 35069585, 2021). "Additionally, as infiltration of immune cells in the tumor microenvironment is known to impact immunotherapy, some authors have been evaluating its relation to LRP1B mutations." (PMID 34577535, 2021). "The putative tumor suppressor gene, LRP1B, is also mutated in both human AS and canine HSA." (PMID 34296746, 2021). "In this study, by analyzing the correlations between clinicopathological characters and TIICs, we found that Treg density infiltration in EC patients had a close association with age, histologic grade, tumor location, histologic type, LRP1B mutation, tumor stage, lymph node stage, and TNM stage." (PMID 32454908, 2020). "A higher tumor mutation burden was found in patients with LRP1B mutations." (PMID 32624706, 2020). "LRP1B is one of the most frequently mutated genes in tumor samples; however, its associations with TMB and prognosis remain unclear." (PMID 31164891, 2019). "Recent studies also revealed LRP1B may as a tumor suppressor in common chemotherpay with deletion mutation of LRP1B causing a chemoresistance and poor outcome." (PMID 31164891, 2019). "The LRP1B gene is a putative tumor suppressor gene encoding an endocytic LDL-family receptor." (PMID 31336878, 2019). "Evidence is mounting that LRP1B may function as a broad-spectrum tumor suppressor, with dysfunction potentially linked to increased tumor invasion and chemotherapeutic resistance." (PMID 27974047, 2016).
tumor (continued). "These structural variants may be important tumor markers or driver genes, such as the large fragment deletion of the LRP1B gene and chromosome 10/16 translocation variants found in several tumors, which are directly related to the degree of tumor malignancy and the selection of therapeutic targets." (PMID 41301752, 2025). "Mutations in EGFR and LRP1B could potentially establish an immune niche that fosters tumor growth." (PMID 38370388, 2024). "Therefore, we speculated that LRP1B mutation was more likely to improve the tumor immune microenvironment to enhance tumor immunogenicity and antitumor immunity in NSCLC." (PMID 36282125, 2023). "Finally, the mechanisms of LRP1B mutations in tumor immunology remain unclear and require further experimental validation." (PMID 36282125, 2023). "In addition to the ETV6-NTRK3 gene fusion, PGR, TERT, DOT1L, KDM5A and LRP1B mutations may be passenger mutations that promote tumor progression." (PMID 36585729, 2022). "Among these genes, PDE4D, LRP1B, CREBBP, and NCOR1 were previously associated with deletions in BC tumor tissue, which favors tumorigenesis or progression." (PMID 40801146, 2025). "Knockdown of LRP1B activates the Hh pathway in tumor cells, leading to the inhibition of several malignant biological behaviors." (PMID 40170839, 2025). "Knockdown of LRP1B can activate the Hh pathway in tumor cells, inhibiting apoptosis and improving proliferation along with other malignant biological behaviors." (PMID 40170839, 2025). "This is consistent with previous studies in other cancer types, where LRP1B mutations have been associated with WNT pathway activation and subsequent tumor progression." (PMID 40599792, 2025). "LRP1B has been found to have a growth suppressive function, which is correlated with its suggested role as a tumor suppressor gene." (PMID 40011914, 2025). "Although segmented amplification has been proposed to achieve overexpression of LRP1B, the varying infectivity of tumor cells and the specificity of antibodies continue to limit its validation." (PMID 40170839, 2025). "Specifically, the expression level of LRP1B was significantly lower in cancer tissues compared to several paired normal tissues, indicating a potential role for LRP1B in inhibiting tumor development." (PMID 40170839, 2025). "Our findings indicated that patients with LRP1B mutations exhibited higher expression levels of CD274, increased abundance of tumor‐infiltrating lymphocytes, elevated TMB, and improved survival outcomes." (PMID 39660409, 2024). "Current studies have shown that LRP1B is widely expressed in normal human tissues and tumor cells, and can regulate tumor cell proliferation, adhesion, differentiation, and angiogenesis." (PMID 39532036, 2024). "Next-generation sequencing (NGS) analysis detected MSI-H, tumor mutation load (TMB) of 17.06 mutations/Mb, and wild-type status for BRAF/NRAS/KRAS, with mutations in β2M and LRP1B." (PMID 39193390, 2024). "LRP1B is a novel candidate tumor suppressor gene, capable of inhibiting tumor cell invasion and metastasis." (PMID 39028418, 2024).
tumor (continued). "LRP1B functions as a tumor suppressor, regulating the extracellular environment to limit cancer cell invasion." (PMID 38731914, 2024). "For tissues where LRP1B is normally expressed, LRP1B is often inactivated in cancer through several genetic and epigenetic mechanisms, making it a putative tumor suppressor gene." (PMID 38769532, 2024). "Our findings offer valuable insights into the molecular mechanisms that govern LRP1B's function in controlling tumor cell death, and further support the possibility of utilizing LRP1B mutation as a biomarker for immunotherapy." (PMID 39660409, 2024). "Lipoprotein Receptor-Related Protein 1B (LRP1B) is a newly discovered candidate tumor suppressor gene." (PMID 39532036, 2024). "Specifically, LRP1B impacted the survival of tumor cells by modulating the phosphorylation level of the transcription factor STAT3, and consequently regulating the expression of SLC7A11." (PMID 39660409, 2024). "Low-density lipoprotein receptor-related protein 1B (LRP1B) is a putative tumor suppressor and a member of the LDL receptor family, a class of proteins that play a role in clearance of extracellular ligand-bound lipids." (PMID 38898085, 2024). "Numerous studies have suggested that decreased expression of LRP1B contributes to tumor initiation and progression, while upregulation of LRP1B suppresses tumorigenesis." (PMID 39660409, 2024). "LRP1B is frequently inactivated by genetic and epigenetic mechanisms, making it a putative tumor suppressor." (PMID 38136305, 2023). "It is concluded that LRP1B expression can stimulate tumor immune cell infiltration, thus bringing clinical benefits to GC patients." (PMID 38136305, 2023). "Immunohistochemistry demonstrated that LRP1B was expressed in the tumor cells (TCs) and immune cells in 16/89 and 26/89 of the cohort, respectively." (PMID 38136305, 2023). "LRP1B is specifically expressed in TCs, making it a novel target to enhance anti-tumor responses and prolong the survival of GC patients." (PMID 38136305, 2023). "Both RNF43 and LRP1B function as tumor suppressors in the Wnt signaling pathway and have been described to be frequently mutated in GC." (PMID 36823311, 2023). "Simultaneously, LRP1B acts as a potential tumor suppressor gene because of its ability to inhibit glycosylation, however, the specific mechanism is not known." (PMID 35389768, 2022). "In sum, our data strongly suggested that downregulation of LRP1B retard HCC tumor progression through the PERK-ATF4-CHOP signaling." (PMID 35389768, 2022). "We further checked the gene expression in primary tumor versus normal tissue for genes JAK2, PRDM16, LRP1B, NIN, and NKX2-1 with variants repeatedly enriched in variant-based analysis, and, FANCE, enriched in gene-based burden testing, using the TCGA database." (PMID 35954343, 2022). "In patients with multiple primary lung cancers, LRP1B alterations were also associated with higher TMB value and positive tumor PDL1 expression." (PMID 35596192, 2022). "Several studies have indicated that LRP1B is a tumor suppressor and show that impaired LRP1B expression promotes carcinoma cell proliferation, migration, and invasion." (PMID 35486034, 2022).
tumor (continued). "In our study, although patients with LRP1B mutation had higher bTMB, CRP, PD-L1 positive rate, and larger tumor size, the association of LRP1B mutation with improved outcomes to ICI plus chemotherapy remained consistent after controlling for these factors." (PMID 35902848, 2022). "In recent years, LRP1B has been proved to participate the antigen presentation and served as a regulatory factor of tumor progression and inflammation." (PMID 35150083, 2022). "In a subsample of patients whose tumours were profiled for RNA (n = 96), feature S(1,−1)SumAverg was significantly associated with the expression of gene MOV10L1, LRP1B, ZFY, PITX2, TRAPPC12, MMGT1 and PPP2R2C (all P < 0.05)." (PMID 36050449, 2022). "A growing number of studies were conducted to demonstrate the involvement of LRP1B in cancer progression and tumor malignancy." (PMID 35389768, 2022). "Our study showed that the downregulation of LRP1B inhibits tumor development by promoting the activation of the PERK-ATF4-CHOP signaling pathway." (PMID 35389768, 2022). "LRP1B plays a critical role in cell adhesion, focal adhesion, and tight junction disruption and further inhibits tumor cell migration and proliferation." (PMID 35488336, 2022). "LRP1B, an endocytic low-density lipoprotein family receptor, is considered to be a candidate tumour suppressor that binds to extracellular ligands." (PMID 36333792, 2022). "Low-density lipoprotein receptor-related protein 1B (LRP1B) has proven to be involved in tumor development and progression of multiple malignancies." (PMID 35389768, 2022). "Remarkably, genomic analysis suggested that the lower tumor mutation burden and gene mutation frequency (e.g., TTN, MUC16, and LRP1B) were found in the high-risk group patients." (PMID 35281096, 2022). "Recurrent laryngeal cancer demonstrated a higher tumor mutation burden (TMB), as well as higher LRP1B mutation and NOTCH1 mutation rates." (PMID 35911687, 2022). "For example, Lrp1b, a putative tumor suppressor, was identified as the gene most frequently affected by point mutations, without an obvious link to the type of exposure." (PMID 35295134, 2021). "The disruption of LRP1B is based on several types of cancers and can be considered as the tumor suppressor." (PMID 34236536, 2021). "LRP1B belongs to the gene family of low-density lipoprotein receptor and is also reputed as a tumor suppressor gene." (PMID 34595167, 2021). "We identified nonsynonymous SNVs in tumor tissues, such as SMARCA4 (in 192D0360T and 192D0641T), BCOR and LRP1B in 192D0641T, as well as frameshift mutations of KMT2D in 192D0695T and truncating mutations of PTCH1 in 192D0583T." (PMID 33707557, 2021). "We detected a homozygous exonic deletion in the LRP1B tumour suppressor gene and four head-to-tail or tail-to-head gene fusions (DNER-TRIP12, SLC12A3-NLRC5, KLHDC4-SLC7A5 and TEAD2-LAIR1)." (PMID 33927198, 2021). "There were 26 cancer-related genes involved in these differentially affected genomic regions, including LRP1B as a putative tumor suppressor gene, and ERBB4 as a member in the EGFR subfamily of receptor tyrosine kinases." (PMID 33902690, 2021).
tumor (continued). "This further contributes to LRP1B endocytic receptor role as a tumor suppressor through modulation of the tumor microenvironment." (PMID 34577535, 2021). "This study aims to identify molecular patterns of LRP1B mutation and HPV status via rewiring tumor samples of HNSCC (n=1478) and CC (n=178) from the TCGA dataset." (PMID 33994859, 2021). "In LRP1B mutant samples, tumor-infiltrating immune cells were more abundant, which indicated a preferable immune response status 46-48." (PMID 33976731, 2021). "LRP1B has been reported to exert tumor suppressor activity, negatively regulating β-catenin/TCF signaling." (PMID 34205480, 2021). "Low-density lipoprotein receptor-related protein 1B (LRP1B) is reputed as a tumor suppressor gene on chromosome 2." (PMID 33994859, 2021). "Most recently, increasing knowledge on LRP1B is pushing towards its relevance cancer, not only as a tumor suppressor gene but further exploring its potential as a target or as a putative translational biomarker." (PMID 34577535, 2021). "In NSCLC, over-expression of full-length LRP1B results in impaired cell proliferation, consistent with hypothetical tumor suppressor function, while LRP1B knockout is the opposite." (PMID 34168983, 2021). "The bioinformatics results show that LRP1B had a frequency of mutation in HCC patients, and LRP1B mutation was associated with a higher tumor mutation burden (TMB), and survival analysis proved that the prognosis of HCC patients with LRP1B mutation was poor." (PMID 34093808, 2021). "LRP1B represents lipoprotein receptor-related protein 1B gene, which has been initiated as a new tumor suppressor candidate gene." (PMID 34386813, 2021). "Tumor mutation burden (TMB) was higher in patients with GC than those with ICC, and was associated with LRP1B mutations (P = .032)." (PMID 32898339, 2020). "HNF1A, ESR1, and FLT4 were mutated significantly more frequently in tumor tissue samples obtained from patients with stage III BC, while SYNE1, PER1, and LRP1B were mutated significantly more frequently in stage IV BC." (PMID 32731384, 2020). "One of its direct targets, the LRP1B gene, is responsible for low-density lipoprotein receptor-related protein 1B and has a tumor suppressor function." (PMID 32102477, 2020). "Although LRP1B has been identified as a tumor suppressor in several cancer types, its expression pattern and biological function in PC remain poorly understood." (PMID 30877185, 2019). "Exonic deletions were detected in the PPP2R5A, FHIT, LRP1B, and OPCML tumor suppressor genes, as well as in genes implicated in cellular proliferation (CCNB1, ANAPC5, PIK3C2A) and DNA repair (SMARCA5)." (PMID 30836646, 2019). "The significantly higher tumor mutation burden and neoantigen burden were observed in aggregated NSCLC samples with LRP1B mutations by Wilcoxon rank sum test (log2 TMB, 8.3 vs. 7.1, P < 0.001; log2 NB, 8.7 vs. 7.4, P < 0.001)." (PMID 31164891, 2019). "For the samples treated with cisplatin, LRP1B copy number, which increases with subclone 1, exhibited a strong correlation with tumor volume change after treatment (r = 0.77, p-val = 0.0008)." (PMID 30560892, 2018). "This study identifies new tumor suppressor genes, LRP1B and TRAF3, with possible interactions with HPV and confirmed the role of TGFBR2 and PTEN in ASCC carcinogenesis." (PMID 29804324, 2018). "Previous studies have demonstrated that LRP1B is a potential tumor suppressor gene and downregulated expression of LRP1B proposed to be involved in multiple primary cancers." (PMID 29181411, 2017). "LRP1B, belonging to the low-density lipoprotein receptor family, was recognized as an important tumor suppressor, and LRP1B under-expression was found in various primary cancers." (PMID 27791988, 2017).